YWHAZP7 (tyrosine 3-monooxygenase/tryptophan 5-monooxygenase activation protein zeta pseudogene 7)
Gene: Processed pseudogene on chromosome X (64,612,632 to 64,613,262, reverse strand). Ensembl gene ENSG00000227261.
Diseases named in the same sentence as YWHAZP7 in open-access papers:
YWHAZP7 is named in the same sentence as 1 disease in open-access papers, as found by Europe PMC text mining. Sharing a sentence is not in itself a finding about the gene and the disease. The quoted sentences say what the papers report.
tumor (1 paper, 2024). "Decreased expression of YWHAZP7 and YWHAZP10 in the platelets of six different tumor tissues is also reported." (PMID 38674334, 2024).